TMEM191B (transmembrane protein 191B)
Tractability: Antibody: UniProt predicts a signal peptide or a membrane-spanning region.
Gene: Protein-coding gene on chromosome 22 (18,527,802 to 18,530,573, forward strand). Ensembl gene ENSG00000278558.
Subcellular location: Membrane
Gene Ontology:
Cellular component: membrane
Genetic constraint (gnomAD): Loss-of-function variants: 3 observed, 2.42 expected, observed/expected ratio (o/e) 1.24, 90% interval 0.5 to 1.9. That is too few expected variants to judge how well the gene tolerates losing a copy. Missense variants: 6 observed, 22.66 expected, observed/expected ratio (o/e) 0.26, 90% interval 0.14 to 0.52. Synonymous variants: 1 observed, 5.23 expected, observed/expected ratio (o/e) 0.19, 90% interval 0.067 to 0.9.
Homologues: Orthologues: chimpanzee TMEM191C (77% identical), rat Tmem191c (54% identical), mouse Tmem191 (53% identical). Paralogues in human: TMEM191C (81% identical).
Diseases named in the same sentence as TMEM191B in open-access papers:
TMEM191B is named in the same sentence as 1 disease in open-access papers, as found by Europe PMC text mining. Sharing a sentence is not in itself a finding about the gene and the disease. The quoted sentences say what the papers report.
bipolar disorder (1 paper, 2023). A disorder of the brain that causes unusual shifts in mood, energy, activity levels and the ability to carry out day-to-day tasks. "Bipolar disorder at 22q11.2 (with single genes models most often explaining variance) showed association with flanking genes on either side, TUBA8, TMEM191B, and PPIL2; PPIL2 appeared in most of the pairs, as well." (PMID 37267418, 2023). "However, we can identify five top genes at 22q11.2 associated with BMI (YDJC, CCDC116, PPIL2, THAP7, UBE2L3), primarily located outside the canonical CNV region (LCR D-E), three with bipolar disorder (TMEM191B, TUBA8, PPIL2), six with ASD (CLTCL1, AC004471." (PMID 37267418, 2023).